ZIC2 (Zic family zinc finger 2)
Diseases named in the same sentence as ZIC2 in open-access papers (continued):
Sharing a sentence is not in itself a finding about the gene and the disease.
prostate carcinoma (10 papers, 2016 to 2025). A carcinoma that arises from epithelial cells of the prostate gland. "A large number of studies have shown that ZIC2 is upregulated in renal cell carcinoma, prostate cancer, oral squamous cell carcinoma, and bladder cancer, in which high expression of ZIC2 is associated with a poor prognosis." (PMID 37479694, 2023). "ZIC2 has shown its involvement in the development of colorectal, breast, nonsmall cell lung, and prostate cancer." (PMID 39428922, 2024). "circDPP4 acted as a miR-564 sponge and indirectly regulated the expression of ZIC2 in prostate cancer." (PMID 37496990, 2023). "It was reported that PCAT92, ABCC4 and ZIC2 are overexpressed in multiple prostate cancer datasets in the public repository (SRP002628 and ERP000550)." (PMID 30197753, 2018). "Out of these not only was ZIC2 among the top three transcription factor based on significance but is also significantly overexpressed in prostate cancer tissues and cell lines like PCAT92 and ABCC4." (PMID 30197753, 2018). "In prostate cancer it has been shown that ZIC2 has functional significance at the molecular and cellular levels in the initiation of prostate adenocarcinoma (PRAD) and the progression to metastatic and/or castration resistant prostate cancer (CRPC)." (PMID 30197753, 2018). "Elevated ZIC2 mRNA expression was described in high Gleason prostate cancer." (PMID 31640781, 2019). "Overall, ZIC2 was identified as an excellent marker and might provide clinically useful predictive information by identification of aggressive prostate cancer subsets." (PMID 31640781, 2019). "Of these three genes, HELLS and ZIC5 protein expression was strongly associated with GS ≥ 7 prostate cancer, while we were not able to confirm this relation on protein level for ZIC2." (PMID 27191985, 2016). "Together, these observations and localization in the nucleus suggests that PCAT92 may play a role in prostate cancer by increasing the local concentration of ZIC2 by forming RNA-DNA triplex near ABCC4 promoter thus helping in recruitment of ZIC2 for ABCC4 regulation." (PMID 30197753, 2018). "In mouse models, the knockdown of MTF1 and the knockout of ZIC2 significantly inhibited tumor growth of cadmium-transformed BPH1 (CTBPH1) cells, suggesting a potential therapeutic strategy for prostate cancer." (PMID 40520016, 2025). "ZIC2 expression was analysed by immunohistochemistry on a tissue microarray (TMA) containing more than 12,000 prostate cancer specimens." (PMID 31640781, 2019). "ZIC5 mRNA was up-regulated 17 fold (p = 8.4E–07), ZIC2 8 fold (p = 1.3E–05) and HELLS 2 fold (p = 0.006) in Gleason grade 3 tumor glands derived from GS 4 + 3 = 7 as compared to GS 3 + 3 = 6 prostate cancer." (PMID 27191985, 2016). "Another prostate cancer cell line, PC3 showed the least expression of ABCC4, PCAT92 and ZIC2." (PMID 30197753, 2018). "Interestingly, we found that ZIC1, ZIC2, ZIC4 and ZIC5 were all up-regulated in Gleason grade 3 embedded in GS 4 + 3 = 7 prostate cancer on RNA level." (PMID 27191985, 2016).
hepatocellular carcinoma (9 papers, 2019 to 2026). A malignant tumor that arises from hepatocytes. "A number of studies reported that SEMA3F, UCK2, NOL10, RAP2A, ZIC2 and SAC3D1 are associated with prognosis and tumour immune infiltration in hepatocellular carcinomas." (PMID 34760691, 2021). "ZIC2 is aberrantly activated in various cancer types, such as hepatocellular carcinoma 19, bladder cancer 26, and cervical cancer." (PMID 32922547, 2020). "ZIC2(Zic family member 2) has been reported to be crucial to the progression of cancer such as hepatocellular carcinoma, epithelial ovarian tumor, osteosarcoma and OSCC." (PMID 31141819, 2019). "Additionally, using qRT-PCR and Western blot, we assessed the expression of ZIC2 in tissues from hepatocellular carcinoma patients and investigated the transcriptional networks of ZIC genes across various cell populations within the tumor microenvironment." (PMID 42045587, 2026). "Although studies on the expression of ZIC2 in hepatocellular carcinoma (HCC) are available, only a few studies have reported the correlation between ZIC2 gene and tumor infiltrating immune cells in the tumor microenvironment." (PMID 33439969, 2021). "High expression levels of certain ZIC genes are associated with poor prognosis and more aggressive cancer phenotypes, as observed with ZIC2 in clear cell renal cell carcinoma and ZIC5 in hepatocellular carcinoma." (PMID 40952541, 2025). "Correspondingly, high expression of the SMARCA1-NURF complex, ZIC2 and OCT4 are positively correlated with the clinicopathological stages of hepatocellular carcinoma (HCC)." (PMID 34736517, 2021).
nasopharyngeal carcinoma (9 papers, 2017 to 2024). A carcinoma arising from the nasopharyngeal epithelium. "miR-873 and miR-129-5p down-regulate ZIC2, and HOXA10 can directly bind to the promoter of ZIC2 and up-regulate ZIC2 transcription in nasopharyngeal carcinoma 22-24." (PMID 37496990, 2023). "In nasopharyngeal carcinoma, the increased expression of ZIC2 leads to increased proliferation, invasion, lymphangiogenesis and lymphatic metastasis of tumor cells, and was an independent prognostic factor of OS and DFS." (PMID 33665207, 2021). "ZIC2 was highly expressed in nasopharyngeal carcinoma compared with normal tissues." (PMID 34660291, 2021). "ZIC2 also overexpressed in oral squamous cell carcinoma, HCC, nasopharyngeal carcinoma and epithelial ovarian cancer, and served as an oncogene in these kinds of cancers." (PMID 34232917, 2021). "ZIC2 and OVOL1 may function in nasopharyngeal carcinoma through targeting significantly up-regulated genes (such as PTGS2, FN1, CXCL9 and CXCL10) in the Transcription factor-differentially expressed gene regulatory network (e.g., ZIC2→PTGS2 and OVOL1→CXCL10)." (PMID 27765529, 2017). "PTGS2, FN1, CXCL9, CXCL10, ZIC2 and OVOL1 might play roles in nasopharyngeal carcinoma." (PMID 27765529, 2017).
cervical cancer (7 papers, 2020 to 2023). A primary or metastatic malignant neoplasm involving the cervix. "Additionally, a recent report showed that ZIC2 is highly expressed in cervical cancer and associated with activation of Hedgehog signaling, a crucial cancer stemness pathway." (PMID 32922547, 2020). "Moreover, function gain and loss analysis of ZIC2 showed that it could improve the Hh signal transduction activity, cell proliferation and anchorage-independent growth ability in cervical cancer cells." (PMID 33665207, 2021). "For example, miR-129-5p inhibits cervical cancer progression by inhibiting ZIC2 via downregulating Hedgehog." (PMID 34692852, 2021).
colorectal cancer (7 papers, 2011 to 2026). A primary or metastatic malignant neoplasm that affects the colon or rectum. "Functional validation demonstrated that ZIC2 overexpression significantly enhanced colorectal cancer cell migration and proliferation, accompanied by upregulation of QPRT." (PMID 41694394, 2026). "In colorectal cancer, ZIC2 modulates TGF-β signaling by inducing TGF-β1 expression and increaings SMAD3 phosphorylation leading to disease progression and metastasis." (PMID 40952541, 2025). "ZIC2 was overexpressed and played an oncogene role in various cancers, such as lung adenocarcinoma, colorectal cancer, and HCC." (PMID 37596527, 2023). "In summary, our findings suggest that BEX2 negatively modulates the hedgehog signaling pathway by retaining Zic2 in the cytoplasm in colorectal cancer cells, thereby inhibiting migration and metastasis of colorectal cancer cells." (PMID 31929751, 2020). "ZIC2 may promote the colorectal cancer progression by upregulating QPRT." (PMID 41694394, 2026). "In contrast, brain-expressed X-linked 2 (BEX2) protein displayed a negative modulation of SHH signaling by retaining ZIC2 in the cytoplasm and inhibiting its nuclear translocation in colorectal cancer cells, hence inhibiting their migration and metastasis." (PMID 40952541, 2025).
lung adenocarcinoma (7 papers, 2020 to 2023). A carcinoma that arises from the lung and is characterized by the presence of malignant glandular epithelial cells. "In lung adenocarcinoma, ZIC2 upregulates OCT4 expression to promote cancer stem cell traits, leading to tumorigenesis and a poor prognosis." (PMID 36518809, 2022). "It is well acknowledged that chemoresistance acts as a hallmark of stem cell-like trait 22, thus, we also investigated the involvement of ZIC2 in drug resistance of lung adenocarcinoma cells." (PMID 32922547, 2020). "Considering that cancer stem cells are responsible for the tumor chemoresistance and the functional roles of ZIC2 in CSCs, the influence of ZIC2 on cisplatin and paclitaxel resistance needed to be deeply investigated in lung adenocarcinoma cells." (PMID 32922547, 2020). "However, the role of ZIC2 as a crucial factor for regulating CSC properties in lung adenocarcinoma (LAC) remains elusive." (PMID 32922547, 2020). "To assess the expression of ZIC2 in lung adenocarcinoma, we quantitatively analyzed both mRNA and protein levels of ZIC2 in 20 LAC tissues and the paired non-cancerous lung tissues." (PMID 32922547, 2020). "Studies have shown that ZIC2 can promote stem cell transformation of lung adenocarcinoma by upregulating the expression of OCT4, which could be utilized as an indicator for monitoring the sensitivity and efficacy of treatment in patients with lung adenocarcinoma." (PMID 37479694, 2023).
colon cancer (6 papers, 2018 to 2025). "However, the functional roles of Zic2 in colon cancer and the underlying molecular mechanism remain elusive." (PMID 34099631, 2021). "Moreover, we noted that some of the mRNAs (ANLN, CFL2, FJX1, HHIP, PANX2, SCN3A, VSNL1 and ZIC2) were also associated with overall survival in patients with colon cancer." (PMID 29420609, 2018). "Altogether, these data indicate that Zic2 is upregulated in colon cancer samples and that high Zic2 expression correlates with unfavorable survival of colon cancer patients." (PMID 34099631, 2021). "Gene Ontology (GO) biological process (BP) analysis confirmed that Zic2 promotes colon tumor growth." (PMID 34099631, 2021). "Intriguingly, we demonstrated for the first time that Zic2 acts as both a transcriptional coactivator and transcriptional repressor in colon cancer." (PMID 34099631, 2021). "We then attempted to reveal the potential mechanism by which Zic2 mediates colon cancer cell proliferation by analyzing the cell cycle and apoptosis." (PMID 34099631, 2021). "Knockdown of Zic2 inhibited colon cancer cell growth, arrested the cell cycle transition from G0/G1 to S phase, and suppressed tumor sphere formation in vitro; in addition, silencing Zic2 retarded xenograft tumor formation in vivo." (PMID 34099631, 2021). "In our study, ectopic expression of Zic2 promoted colon cancer proliferation by activating cyclin D1 transcription, in addition to cell cycle transition from G0/G1 to S phase in vitro." (PMID 34099631, 2021). "High expression of Zic2 protein was correlated with poorer overall survival (OS) than low expression of Zic2 in colon cancer patients." (PMID 34099631, 2021). "Taken together, these results led us to conclude that Zic2 promotes colon cancer growth by activating Wnt signaling via interaction with β-catenin and repression of Axin2." (PMID 34099631, 2021). "In summary, we demonstrated that Zic2 is upregulated in colon cancer samples and that high Zic2 expression correlates with unfavorable survival of colon cancer patients." (PMID 34099631, 2021). "Collectively, in addition to directly repressing Axin2 transcription, Zic2 also interacts with β-catenin to activate Wnt signaling in colon cancer." (PMID 34099631, 2021). "Collectively, these results indicate that Zic2 exerts multilevel regulation on Wnt signaling through interaction with β-catenin and repression of Axin2 in colon cancer." (PMID 34099631, 2021). "Zic2 functions in colon cancer, at least in part, by enhancing Wnt/β-catenin signaling via collaboration with β-catenin and repressing Axin2." (PMID 34099631, 2021). "Collectively, these data indicate that Zic2 promotes colon cancer proliferation by inducing a transition from G0/G1 to S phase rather than by impacting apoptosis." (PMID 34099631, 2021). "By multivariate analysis, we found that Zic2 was an independent prognostic factor for poor OS in colon cancer patients." (PMID 34099631, 2021). "The results showed that Zic2 transcript levels were upregulated in colon cancer compared with normal colon tissues in the GSE44706 mRNA microarray dataset and TCGA RNA-sequencing data." (PMID 34099631, 2021). "In our study, a similar conclusion was drawn in colon cancer, and this is the first analysis of the relationship between Zic2 and prognosis using human colon cancer samples." (PMID 34099631, 2021). "The inverse correlation between Zic2 and Axin2 was further validated by IHC analysis of human colon cancer samples." (PMID 34099631, 2021). "To explore the role of Zic2 in colon cancer, we first analyzed the expression of Zic2 between colon cancer and normal colon tissues by bioinformatic analysis." (PMID 34099631, 2021). "To further validate the role of Zic2 in colon cancer, we performed IHC staining using another independent cohort of 403 colon cancer patient samples (cohort II)." (PMID 34099631, 2021). "Herein, we demonstrated that Zic2 was highly expressed in colon cancer tissues and correlated with poor survival." (PMID 34099631, 2021).
colon cancer (continued). "Mechanistically, Zic2 executed its oncogenic role in colon cancer by enhancing Wnt/β-catenin signaling." (PMID 34099631, 2021). "Altogether, our findings uncover a novel multilevel mechanism for the oncogenic activity of Zic2 in colon cancer and suggest Zic2 as a potential therapeutic target for colon cancer patients." (PMID 34099631, 2021). "We observed that the size and number of spheres in Zic2-silenced colon cancer cells were remarkably decreased compared with those in control cells." (PMID 34099631, 2021). "The expression of Zic2 was measured in six established colon cancer cell lines and one human colonic epithelial cell line (HCoEpiC) by western blotting and qRT-PCR analysis." (PMID 34099631, 2021). "Zic2 protein was mainly localized in the nucleus of cells in colon cancer tissues and colon cancer cell lines." (PMID 34099631, 2021). "A recent study indicated that Zic2 can render colon cancer cells more resistant to low-glucose-induced apoptosis by activating Wnt signaling." (PMID 34099631, 2021). "We found that Zic2 transcript levels were higher in all six colon cancer cell lines than in HCoEpiC." (PMID 34099631, 2021). "KIF26A and ZIC2 gene expression, with which shRNA efficacy displayed significant scores, were found to correlate with the survival rate from colon cancer patient data." (PMID 33114107, 2020). "ZIC2 was demonstrated to activate Wnt/β-catenin signaling by Zic2 directly interacting with β-catenin and by transcriptionally repressing Axin2 expression and consequently promoting the accumulation and nuclear translocation of β-catenin in colon cancer." (PMID 40952541, 2025). "Our results demonstrate that Zic2 promotes colon cancer proliferation and CSC properties." (PMID 34099631, 2021). "To confirm the role of Zic2 proteins in colon cancer, we performed immunohistochemical (IHC) staining of 180 colon cancer samples via a tissue microarray (cohort I) and found a markedly increased protein level of Zic2 in colon cancer tissues compared with adjacent colon normal tissues (P < 0.0001)." (PMID 34099631, 2021). "Our results indicate that Zic2 promotes the proliferation and tumorigenesis of colon cancer." (PMID 34099631, 2021). "A recent study indicated that Zic2 could render colon cancer cells more resistant to low glucose-induced apoptosis." (PMID 34099631, 2021). "Taken together, the data show that Zic2 enhances Wnt signaling activity in colon cancer." (PMID 34099631, 2021). "All of these results indicate that Zic2 could bind to specific areas of the Axin2 promoter and transcriptionally activate Axin2 in colon cancer cells." (PMID 34099631, 2021). "Zic2 might be a potential prognostic marker in colon cancer because higher Zic2 transcript levels were strongly correlated with poorer overall survival in TCGA data." (PMID 34099631, 2021). "Our study revealed multilevel regulation of Wnt signaling by Zic2 in colon cancer." (PMID 34099631, 2021). "GO molecular function analysis suggested that Zic2 might execute its biological function in colon cancer via DNA/protein binding and transcription regulator activity." (PMID 34099631, 2021). "Furthermore, KIF26A and ZIC2 gene expression, with which shRNA efficacy displayed significant scores, were found to correlate with the survival rate from colon cancer patient data." (PMID 33114107, 2020). "Therefore, we hypothesized that Wnt signaling might be involved in Zic2-mediated colon cancer growth promotion." (PMID 34099631, 2021). "Zic2 might enhance Wnt/β-catenin signaling in colon cancer via chromatin remodeling." (PMID 34099631, 2021). "In the present study, we identified that Zic2 enhances Wnt signaling and initiates the transcription of several novel downstream target genes, including cyclin D1, CD44, and Lgr5, which promote proliferation and stemness in colon cancer cells." (PMID 34099631, 2021). "Intriguingly, modulation of Zic2 expression did not affect the apoptosis rate in colon cancer cells." (PMID 34099631, 2021).
bladder cancer (5 papers, 2020 to 2023). "HULC promoted bladder cancer cells proliferation but inhibited apoptosis via regulation of ZIC2 and PI3K/AKT signaling pathway." (PMID 32010942, 2020).
clear cell renal cell carcinoma (5 papers, 2021 to 2025). "Mechanistically, previous studies have shown that ZIC2 is highly expressed in clear cell renal cell carcinoma (ccRCC) and promotes the proliferation and migration of ccRCC by regulating the expression of the downstream target gene Runx2 and the ZIC2/Runx2/NOLC1 signaling axis." (PMID 37479694, 2023). "However, the prognosis, tumor promoting effect and regulatory mechanism of ZIC2 in clear cell renal cell carcinoma (ccRCC) are still unknown." (PMID 37496990, 2023).
microcephaly (4 papers, 2019 to 2025). A congenital or acquired developmental disorder in which the circumference of the head is smaller than normal for the person's age and sex. "MIR17HG and ZIC2 loss was observed in a patient with digital anomalies, severe growth failure, microcephaly and corpus callosum agenesis while hemizygotic EFNB2 gene loss was identified in two patients, one of them with microphtalmia." (PMID 31976095, 2019). "The role of ZIC2 in neurulation has been well characterized in vivo in mouse 53,54 and genetic variants of SOX11 in humans have been associated with midline defects, microcephaly and ocular malformations 64,65." (PMID 40777478, 2025).
oral squamous cell carcinoma (4 papers, 2015 to 2026). "To date, ZIC2 over-expression was reported to impact the clinical course and prognosis of patients harboring ovarian cancer, endometrial cancer and oral squamous cell carcinoma, while the molecular mechanism of disease progression was not revealed." (PMID 26318045, 2015).